MPO (myeloperoxidase)
Diseases named in the same sentence as MPO in open-access papers (continued):
Sharing a sentence is not in itself a finding about the gene and the disease.
colitis (continued). "However, in the uninflamed ileum from the colitis animals, the level of MPO activity remained unchanged." (PMID 31694264, 2019). "Also, the mucosal activity of myeloperoxidase, a biochemical marker of leukocyte inflammatory infiltration, was significantly reduced in animals with colitis and treated with ghrelin in comparison with animals with colitis and treated with a placebo." (PMID 30934722, 2019). "The colonic MPO concentrations in the colitis group were significantly increased." (PMID 31221091, 2019). "GOS (4 g/Kg/day) administration for 10 days increase bifidobacterial number in colon in a TNBS colitis induced murine model, but it was not linked with a reduction of pro-inflammatory markers as MPO activity and colon damage." (PMID 30987294, 2019). "Prevention of the DSS-induced increase in MPO concentrations indicates that Frondanol prevents the accumulation of polymorphonuclear granulocytes in DSS-induced colitis tissue, since MPO activity reflects the increase in neutrophil accumulation in the submucosa due to the severity of colitis." (PMID 29710854, 2018). "In a model of colitis induced in mice by intracolonic administration of dinitrobenzene sulphonic acid (DNBS), CBG was able to reduce colon weight/colon length ratio, myeloperoxidase activity and exerts an anti-inflammatory activity associated to DNBS administration." (PMID 29986533, 2018). "Similarly, treatment with 1.5% dried whole cranberry powder (incorporated in the diet) reduced MPO activity in the colon of mice submitted to dextran sulphate sodium-induced colitis." (PMID 29861777, 2018). "Moreover, fortunellin (5 or 80 mg/kg) reversed the excessive pro-inflammatory cytokine (TNF-α, IL-1β, and IL-6) profiles and MPO activity in the TNBS-induced colitis model." (PMID 29472916, 2018). "The elevated MPO activity was significantly suppressed in the p85α+/− colitis mice." (PMID 28733636, 2017). "Induction of colitis led to an increase in colonic activity of myeloperoxidase." (PMID 28538694, 2017). "MMDP extract potently suppressed colon shortening and MPO in mice with TNBS-induced colitis." (PMID 28946886, 2017). "Furthermore, miR-206 increased dextran sodium sulphate-induced colitis severity (i.e., increased bodyweight loss, DAI score, colon shrinkage, and MPO activity), which was partially ameliorated by miR-206-antagomir treatment." (PMID 27893428, 2017). "Indeed, studies using different protocols to induce colitis have demonstrated a positive correlation between the determination of MPO activity and disease severity." (PMID 28194046, 2017). "We also obtained similar results in a colitis mouse model, wherein miR-206 increased the severity of DSS-induced colitis, measured as enhanced bodyweight loss, DAI score, colon shrinkage, and MPO activity, whereas miR-206-antagomir treatment partially ameliorated these effects." (PMID 27893428, 2017). "Compared with the healthy control, MPO activity was increased in the colon of colitis-induced mice." (PMID 28842625, 2017). "Moreover, in hypophysectomized rats, administration of ghrelin failed to affect serum levels of GH or IGF-1, as well as the healing rate of colitis, mucosal cell proliferation, and mucosal concentration of IL-1β, or activity of myeloperoxidase." (PMID 28538694, 2017). "In addition, DSS increased the serum and colonic MPO activity, while aloperine suppressed the serum and colonic MPO activity in murine colitis." (PMID 29056830, 2017). "As such, myeloperoxidase levels weresignificantly increased in the intestine ofCrh−/− 7d DSS vs. WT 7d DSS, whereas a number ofcytokines associated with colitis, were expressed at higher levels in theintestine of Crh −/− 7d DSS vs. WT 7d DSS mice." (PMID 26987580, 2016). "Also, after the next 7 days, almost 2-fold increase in myeloperoxidase activity was still observed in colonic mucosa in rats with colitis treated with saline." (PMID 26798415, 2016).
colitis (continued). "In the present study, we generated colitis in mice by TNBS, which resembled human inflammatory bowel disease in weight loss, diarrhea, bloody stool, and increased DAI, macro and microscopic score and MPO." (PMID 26728323, 2016). "Additionally, 14 days after the induction of colitis, myeloperoxidase activity in colonic mucosa was still almost a two-fold higher than in control animals." (PMID 27598133, 2016). "The beneficial effect of CBD BDS on DNBS-induced colitis was further confirmed by the MPO results." (PMID 27757083, 2016). "Interestingly, O-1918 administration alone increased colitis scores and MPO activity beyond that of controls, which suggests that the actions of an endogenously active anti-inflammatory endocannabinoid were inhibited by O-1918." (PMID 27418880, 2016). "The addition of 4mM DCA enema caused much more severe colitis than DSS treatment alone, as evidenced by significant decrease of body weight and shortening of colon length, much higher haematochezia score, and MPO activity." (PMID 27965665, 2016). "It should be noted, however, that the treatment-related patterns of cytokine concentrations in the brain do not match with the patterns of plasma cytokine concentrations and other markers of colitis (MPO, DAS), suggesting a central effect of WAS to promote neuroinflammation." (PMID 26066467, 2015). "Oral administration of QDP suppressed colonic macrophage recruitment and activation to attenuate the severity of DSS-induced colitis in mice, as evidenced by reduced mortality, clinical manifestations, colon shortening, histological damage and colonic myeloperoxidase activity." (PMID 26464580, 2015). "In accord with this evidence, MPO activity was shown to significantly increase in rat colonic tissue with DSS-induced colitis, and the XLS treatment prevented this increase, a finding indicative of a reduction in neutrophilic infiltration and a decrease in colon damage." (PMID 25120575, 2014). "Furthermore, DSS induces neutrophil infiltration in the colon leading to increasing colonic MPO activity, which is treated as another inflammatory marker for colitis." (PMID 24504372, 2014). "The aim of this study was to evaluate the action of glucans from the Caripia montagnei model on 2,4,6-trinitrobenzene sulfonic acid (TNBS)-induced colitis in rats and their effects on interleukin levels (IL-1 IL-6), catalase, myeloperoxidase (MPO) enzymes and nitric oxide." (PMID 24518681, 2014). "Intracolonic administration of vehicle (30% ethanol in saline) produced a minor inflammation, which was significantly different from the TNBS-induced colitis (macroscopic damage score 6.07±0.21, microscopic score 10.3±0.7, MPO activity 39.7±3.1 units in TNBS-treated mice, n = 5–6)." (PMID 25275313, 2014). "To determine whether AITC affects infiltration of inflammatory cells in DSS-induced colitis we measured MPO activity, and number of F4/80 positive cell." (PMID 25051185, 2014). "Similar inhibition on MPO activity was also reported in colitis treated with T. spiralis infection." (PMID 24788117, 2014). "The curative administration of SmSWP (started when colitis was established), resulted in a significant improvement of the clinical disease score, colonoscopy, macroscopic and microscopic inflammation score, colon length and myeloperoxidase activity." (PMID 25313594, 2014). "Further, we assessed additional indicators of colitis such as colon length and MPO activity." (PMID 24040033, 2013). "Therefore, to investigate the effects of γ-PGA on neutrophil infiltration in DSS-induced colitis, we measured MPO activity." (PMID 23766568, 2013). "In the rat model of colitis induced by rectal administration of DNBS, rivastigmine caused a dose related reduction in the area of ulceration and number of colonic ulcers and in TBARS (a measure of oxidative stress) colonic MPO and ChE activity." (PMID 23469045, 2013).
colitis (continued). "Similarly, MPO activity in the dextran sodium sulfate (DSS)-induced colitis model was 22 times higher, and TNF-α level in plasma was approximately 100 times higher than that for the control group." (PMID 24001404, 2013). "Also MPO is one of the indicators of inflammation and it is well correlated with neutrophil infiltration in various colitis models." (PMID 23125487, 2012). "Although the ingestion of the S-IMO and Dex diets delayed the development of colitis, the effects on the increases in ratio of colon weight per length and MPO activity were different between the rats fed the S-IMO diet and the rats fed the Dex diet in this experiment." (PMID 23209802, 2012). "Indeed, oral administration of FSG starting from the day of TNBS instillation to 5 days later resulted to a significant decrease in MPO activity on days 3 and 5 post-colitis." (PMID 23166707, 2012). "In addition, FSG given in a curative way in female rats (from TNBS administration until 5 days post-TNBS) decreased MPO activity on days 3 (p<0.01) and 5 (p<0.05) after induction of colitis." (PMID 23166707, 2012). "Levels of MPO in the colons of WT colitis mice were significantly higher than control mice." (PMID 23285227, 2012). "The protective effects of IG on dextran sulfate sodium (DSS)-induced colitis were assessed by macroscopic score and histological analysis as well as by determination of inflammation markers such as MPO activity and the mRNA expressions of pro-inflammatory cytokines such as TNF-α and IL-8." (PMID 21931839, 2011). "In the same study, chronic administration of anti-VCAM-1 antibody, but not anti-ICAM-1 or anti-MAdCAM-1, resulted in significant attenuation of colitis in terms of disease activity index, colon length, ratio of colon weight to length, and myeloperoxidase activity." (PMID 22073270, 2011). "However, 1-week CTX treatment after the establishment of colitis by 4% DSS still produced significantly greater colonic MPO activity compared to 1-week-vehicle-treated controls." (PMID 22220274, 2011). "Colitis was assessed by clinical score, histological score and myeloperoxidase activity." (PMID 18836554, 2008). "Administration of T. spiralis crude larval antigen extract before induction of colitis reduced colitis severity as demonstrated by reduced colon weight-to-length ratio, improved macroscopic and microscopic scores, increased colonic IL-10 expression, and diminished colonic MPO protein expression." (PMID 40830617, 2025). "Furthermore, the colons of GSDME-deficient mice contained fewer infiltrating MPO+ neutrophils and F4/80+ macrophages in DSS-induced colitis, indicating that GSDME contributes to DSS-induced colitis through recruiting inflammatory immune cells and initiating inflammatory responses." (PMID 40103680, 2025). "For instance, Lactobacillus rhamnosus 1.0320 combined with inulin can alleviate colitis caused by DSS, reduce the disease activity index score of colon tissue damage, and increase IL-10 expression while downregulating IL-1β, IL-6, TNF-α, and myeloperoxidase (MPO)." (PMID 40521353, 2025). "Indeed, our prior preliminary work indicated that A. bisporus WMP pretreatment could reduce IL‐1β and IL‐6, and MPO activity in the proximal colon of a murine DSS‐induced colitis model." (PMID 40509652, 2025). "Additionally, we evaluated the expression of MPO in the colonic tissues of colitis rats." (PMID 41008172, 2025). "Additionally, myeloperoxidase levels were higher in acute betanin-supplemented and unsupplemented colitis-affected rats compared to healthy rats, but myeloperoxidase levels in betanin-supplemented rats were lower than in other colitis-affected rats." (PMID 41515203, 2025). "Treating experimentally induced colitis in mice with blueberry anthocyanin extract has been shown to promote the production of IL-10 and decrease the levels of nitric oxide (NO), myeloperoxidase (MPO), IFN-γ, IL-12, and TNF-α, indicating the potential anti-inflammatory properties of berry compounds." (PMID 39502877, 2024).
colitis (continued). "In this study, we show that C:15 administration for 3 weeks prior to DSS induction elicits a protective effect against colitis severity, specifically protecting mice against weight loss and resulting in lower fecal MPO activity when compared to non-treated mice." (PMID 39275347, 2024). "The MPO activity was elevated nearly twofold in colitis mice compared to their healthy counterparts, yet it was markedly suppressed, by a factor of 2.3, in the P5 and P10 groups compared to colitis mice, underscoring the considerable anti-inflammatory impact of LCP." (PMID 37761037, 2023). "They showed that it could reduce MDA, NO, MPO, hydroxyproline, TNF-α, IL-1β, IL-6, iNOs mRNA, COX-2 mRNA, IFN-γ mRNA, Bcl-2-associated X protein (Bax), Caspase-1, NF-kB and IκBα and increase IL-10, SOD and GSH in an in vivo model of TNBS-induced colitis." (PMID 36677021, 2023). "Additionally, colitis mice displayed a significant increase in colonic MPO level." (PMID 37774039, 2023). "In addition, in vivo antioxidant activity was evaluated by measuring superoxide dismutase (SOD), glutathione peroxidase (GSH-Px), catalase (CAT), myeloperoxidase (MPO) activity, and malondialdehyde (MDA) levels in the context of secondary liver caused by DSS-induced colitis." (PMID 36900632, 2023). "Specifically, MPO activity and ROS production were negatively correlated with β-hydroxybutyrate levels, implying that β-hydroxybutyrate may reduce oxidative stress, which is often increased in colitis and contributes to gut inflammation." (PMID 37513865, 2023). "Interestingly, also memantine acting by blocking N-methyl-D-aspartate (NMDA) receptors significantly attenuates macroscopic and microscopic signs of colitis in a mouse model decreasing the plasma levels of interleukin-1β, interleukin-6, and colon level of tumor necrosis factor-α and myeloperoxidase." (PMID 34797427, 2022). "Moreover, treatment of the experimentally induced colitis models with active flavonoids greatly reduced neutrophil infiltration into the injured colonic tissue, as proved by a significant decline in colonic myeloperoxidase, thus contributing to the attenuation of intestinal inflammation." (PMID 35884960, 2022). "Therefore, MPO can be considered one of the essential indicators of inflammation in colitis." (PMID 36615796, 2022). "In addition to MPO, there was a significant rise in the levels of calprotectin, a protein found in the cytosol of inflammatory cells, following activation of leukocytes that display intestinal inflammation and progression of colitis." (PMID 35566122, 2022). "Its increased luminal or fecal but not mucosal activity might indicate that micro-inflammation is still present in the post-colitis rats, although other inflammatory parameters (colonoscopy, histological examination, and MPO activity) were normalized on the day of VMR experiments." (PMID 34072320, 2021). "Furthermore, F. prausnitzii (strain A2-165) or its supernatant has been confirmed to induce a significant reduction in colitis severity by downregulating MPO, pro-inflammatory cytokines, and T-cell levels, and protecting the intestinal epithelial barrier in colitis mouse models." (PMID 33641084, 2021). "Furthermore, a rat model of DSS-induced colitis exposed to 8 mg/kg of deoxynivalenol in their diet for 4 weeks induced a more rapid and severe onset of colitis than controls and induced significant increases in pro-inflammatory markers (myeloperoxidase, CXCL-1, and IL-1β)." (PMID 33927703, 2021). "We found that PLPs, Caffeic acid, and P-coumaric acid significantly reduced MPO activity in the colitis model; thus, the anti-inflammatory effects presented by PLPs, Caffeic acid, and P-coumaric acid could be evidenced by the significant reduction in intraepithelial immune cell infiltration." (PMID 34946738, 2021).
colitis (continued). "However, oral gavage of NK210 or NK219 suppressed LPS-induced colitis: they decreased myeloperoxidase activity, NF-κB+/CD11c+ cell population, and IFN-γ to IL-10 and TNF-α to IL-10 expression ratios in the colon while colon shortening was not significantly increased." (PMID 34667205, 2021). "To determine whether the dosing time-dependent anti-colitis effects of CR in mice are associated with berberine and REV-ERBα, we measured colonic MDA and MPO activities as well as IL-1β and IL-6 levels in Rev-erbα−/− mice with colitis after 7 days’ CR treatment." (PMID 34393786, 2021). "Furthermore, marked elevation was detected in MPO activity in experimental colitis group." (PMID 33061833, 2020). "Furthermore, the reduction in MPO activity by SLBZS improved colitis." (PMID 32547403, 2020). "Also, green tea administration up-regulates HO-1 expression in the colon, which may contribute to the protective effects in 2,4,6-dinitrobenzenesulphonic acid–induced colitis model by reduction of colonic myeloperoxidase (MPO) and TNF-α production." (PMID 32849503, 2020). "Therefore, MPO can be used to evaluate disease severity in colitis." (PMID 32595641, 2020). "DSS-induced colitis reproduces several pathophysiologic features of UC such as increased expression of interleukin (IL)-6, IL-10 and tumor necrosis factor-α, elevated colonic levels of myeloperoxidase (MPO), inflammatory histopathology, bloody diarrhea and a decrease of ingestion." (PMID 32451393, 2020). "Thus, we speculated that SCN− supplementation would confer protection during experimental colitis by redirection of MPO halogenation to favour HOSCN production above HOCl." (PMID 32899436, 2020). "DSS administration caused severe colitis characterized by worsening of DAI score and of the local parameters of inflammation and damage: colon length was markedly decreased, whereas colon thickness and colonic myeloperoxidase activity were significantly augmented." (PMID 31297055, 2019). "Although Cnb1CD11c mice did not develop evident symptoms of colitis (such as weight loss, diarrhea or rectal bleeding), they exhibited significantly higher intestinal permeability, titers of fecal IgA, and myeloperoxidase activity in homogenates of the terminal ileum than Cnb1fl/fl controls." (PMID 29549257, 2018). "Furthermore, because this form of colitis is clearly tied to the immune system, colon cytokine concentrations, lymphocyte levels, and myeloperoxidase (MPO) activity (indicator of neutrophil infiltration that reflects the local immune response) are helpful markers of colitis severity." (PMID 29636738, 2018). "Thus, the DSS-induced colitis resulted in an increase in MPO, INF-γ, IL6, IL1-β, TNF-α, and IL10." (PMID 28528363, 2018). "The results showed that serine decreased the disease activity index, as well as myeloperoxidase, eosinophil peroxidase, and proinflammatory cytokine concentrations in colonic tissue, while serine improved colonic morphology and inhibited cell apoptosis in colitis mice." (PMID 30619148, 2018). "Likewise, treatment with fraxinellone, a natural lactone endowed with immunosuppressive activity, significantly reduced weight loss, diarrhea and colonic macroscopic damage, as well as myeloperoxidase, alkaline phosphatase, and colonic TNF, IL-1β, IL-6, and IL-18 levels in DSS-induced colitis mice." (PMID 28179906, 2017). "After necropsy, examination of the colon found that during the acute colitis Acer3−/− mice had earlier and greater colonic shortening, compared with Acer3+/+ mice, higher scores of colonic epithelial damage and inflammatory infiltration, and a greater colonic myeloperoxidase (MPO) activity." (PMID 26938296, 2016). "Similarly, we also found significantly elevated MPO levels in TNBS-induced colitis rats." (PMID 27822176, 2016).